SH2D4A (SH2 domain containing 4A)
Description:
Inhibits estrogen-induced cell proliferation by competing with PLCG for binding to ESR1, blocking the effect of estrogen on PLCG and repressing estrogen-induced proliferation. May play a role in T-cell development and function.
Synonyms: PPP1R38; SH2A; FLJ20967
Tractability: PROTAC: ubiquitination databases record sites on it.
Gene: Protein-coding gene on chromosome 8 (19,313,693 to 19,396,695, forward strand). Ensembl gene ENSG00000104611.
Subcellular location: Cytoplasm
Subcellular location (Human Protein Atlas): Cytosol
Gene Ontology:
Molecular function: phosphatase binding; protein binding; protein-macromolecule adaptor activity
Cellular component: cytosol; cytoplasm
Genetic constraint (gnomAD): Loss-of-function variants: 55 observed, 54.65 expected, observed/expected ratio (o/e) 1.01, 90% interval 0.81 to 1.26. The synonymous counts are far from expectation, so gnomAD's model fits this gene poorly and the ratio says little. Missense variants: 606 observed, 493.33 expected, observed/expected ratio (o/e) 1.23, 90% interval 1.15 to 1.31. Synonymous variants: 242 observed, 187.2 expected, observed/expected ratio (o/e) 1.29, 90% interval 1.16 to 1.44.
Homologues: Orthologues: chimpanzee SH2D4A (98% identical), macaque SH2D4A (94% identical), guinea pig SH2D4A (80% identical), rabbit SH2D4A (78% identical), dog SH2D4A (73% identical), rat Sh2d4a (73% identical), mouse Sh2d4a (73% identical), tropical clawed frog sh2d4a (50% identical), Caenorhabditis elegans F13B12.6 (31% identical), zebrafish sh2d4a (21% identical). Paralogues in human: SH2D4B (43% identical), SH2D7 (12% identical), HSH2D (11% identical), SH2D2A (10% identical).
Diseases named in the same sentence as SH2D4A in open-access papers:
SH2D4A is named in the same sentence as 11 diseases in open-access papers, as found by Europe PMC text mining. Sharing a sentence is not in itself a finding about the gene and the disease. The quoted sentences say what the papers report.
glioma (2 papers, 2023). A benign or malignant brain and spinal cord tumor that arises from glial cells (astrocytes, oligodendrocytes, ependymal cells). "Moreover, we discovered that SH2D4A, one of the risk hub genes, could stimulate the migration and proliferation of glioma cells." (PMID 37698534, 2023). "By screening differentially expressed genes, and performing WGCNA, LASSO, and multivariate Cox regression analyses, we identified risk hub genes (RAB42, SH2D4A, and GDF15) associated with glioma stemness, genomic heterogeneity, and the immune microenvironment." (PMID 37698534, 2023). "To investigate the effect of SH2D4A on glioma cells, we knocked down SH2D4A in U87 MG cells by transfecting specific siRNAs." (PMID 37698534, 2023). "The expression of three risk hub genes in glioma was investigated in the TCGA and CGGA datasets, and RAB42, SH2D4A, and GDF15 were found to be higher expressed in GBM than in LGG." (PMID 37698534, 2023). "Given the conflicting roles of SH2D4A in different tumor types, we validated its effects on glioma cells." (PMID 37698534, 2023). "Although SH2D4A appears to play opposing roles in tumors, our experiments demonstrated that knockdown of SH2D4A significantly inhibited the migration and proliferation of glioma cells." (PMID 37698534, 2023). "However, the effects and mechanisms of SH2D4A on glioma stemness and microenvironment needs to be further investigated." (PMID 37698534, 2023). "Through WGCNA, LASSO and multivariate Cox regression analyses, we identified RAB42, SH2D4A and GDF15 as high-risk hub genes for glioma, and we employed these genes to create a risk model that showed high sensitivity and specificity in prognosticating patients’ 1-, 3-, and 5-year survival." (PMID 37698534, 2023). "Our results suggest that SH2D4A contributes to the migration and proliferation of glioma cells." (PMID 37698534, 2023). "In the TCGA and CGGA datasets, the Kaplan-Meier curve showed that RAB42, SH2D4A, and GDF15 significantly affected the prognosis of glioma, with a poor prognosis at high expression." (PMID 37698534, 2023). "Moreover, SHOX2 and SH2D4A were highly expressed in glioma cell lines, but the difference was not obvious." (PMID 37091145, 2023). "However, the function of SH2D4A in glioma has not been reported in the literature so far." (PMID 37698534, 2023).
hepatocellular carcinoma (2 papers, 2023). A malignant tumor that arises from hepatocytes. "Furthermore, some cases of hepatocellular carcinomas (HCCs) with loss of chromosome 8p exhibits poor prognosis, in which six genes including SH2D4A are down-regulated." (PMID 36739326, 2023). "Src homology 2 domain-containing 4A (SH2D4A) is located on chromosome 8p, which is commonly deleted in various cancer entities including breast cancer, prostate cancer, and hepatocellular carcinoma and has been shown to correlate with poor patient survival." (PMID 37091145, 2023).
tumor (7 papers, 2020 to 2023). "In this study, we aimed at identifying new interaction partners of SH2D4A to functionally uncover the underlying molecular mechanisms of its tumor-suppressive function." (PMID 33257655, 2020). "The methylation of HOXA1, IGFBP2, PTX3, TIMP1, SHOX2, and SH2D4A decreases with increasing tumor grade." (PMID 37091145, 2023). "SH2D4A was identified as a chromosome 8p tumor suppressor and positively correlated with effector and regulatory T cell infiltration by blocking IL-6 signaling in HCC, which implies its crucial role in HCC." (PMID 36147313, 2022). "Recently, we found that the chr8p tumor suppressor SH2D4A interacts with STAT3 outside the nucleus thereby inhibiting tumor-promoting STAT3 signaling." (PMID 33257655, 2020). "We found that SH2D4A and PHB1 co-localize in mitochondria and treatment of tumor cells with the PHB ligand FL3 reduced SH2D4A, STAT3, and PHB1 protein levels but led to increased co-localization of PHB1 and pSTAT3-Ser727." (PMID 33257655, 2020). "Moreover, the risk signature and risk hub genes RAB42, SH2D4A, and GDF15 were highly positively correlated with the increase of these immunosuppressive tumor infiltrating cells." (PMID 37698534, 2023). "Recently, we demonstrated that the chr8p gene SH2D4A (Src homology 2 domain-containing 4A) exhibits tumor-suppressive functions in vivo and in vitro by inhibiting the Interleukin-6 (IL-6) induced Signal Transducer and Activator of Transcription 3 (STAT3) signaling pathway in HCC5,6." (PMID 33257655, 2020). "In addition, FL3 reduced mitochondrial respiration, whereas deletion of SH2D4A in tumor cells increased mitochondrial respiration and FL3 treatment counteracted this effect." (PMID 33257655, 2020). "Other genes, such as SH2D4A, BCLAF1, and SUV420H, also have carcinogenic or tumor-suppressing functions that can affect the formation and development of human cancer." (PMID 32079071, 2020). "Loss of 8p involving the DLC1, CCDC25, ELP3, PROSC, SORBS3, SH2D4A genes associated with poor outcomes for HCC; in vitro and in vivo analysis indicated that the PROCS, SH2D4A and SORBS3 genes have tumor-suppressive activities and the DLC1 gene is a known tumor suppressor gene." (PMID 34103027, 2021). "Taken together, we demonstrated that the tumor suppressor SH2D4A is linking STAT3 nuclear and mitochondrial functions, and inhibition of PHB-binding may have therapeutic effects in tumor cells with STAT3 activation." (PMID 33257655, 2020). "The demonstrated interaction with STAT3, accompanied by its reduction of transcriptional activity, further suggests that SH2D4A is linking STAT3 to its mitochondrial functions, and inhibition of PHB-interaction may have therapeutic effects in tumor cells with STAT3 activation." (PMID 33257655, 2020). "Here, we investigated the interaction of SH2D4A and STAT3 to shed light on the non-canonical functions of STAT3 in cooperation with the tumor suppressor SH2D4A." (PMID 33257655, 2020).
cancer (6 papers, 2020 to 2023). A tumor composed of atypical neoplastic, often pleomorphic cells that invade other tissues. "Earlier studies indicate that chromosome regions harboring SH2D4A are frequently deleted in various cancer types, and the deletion or downregulation of this gene is related to poor survival and hepatocarcinogenesis." (PMID 37698534, 2023). "Thus, SH2D4A is a novel protein involved in mitochondrial function and inhibition of mitoSTAT3/PHB1 in cancer patients with deletion of SH2D4A may be therapeutically relevant." (PMID 33257655, 2020). "SH2 domain-containing protein 4A (SH2D4A/PPP1R38) is a member of SH2 signaling protein family and is involved in the IL-6 signaling in cancer cells." (PMID 36739326, 2023).
SH2D4A also shares sentences with these, for which no sentence is quoted: breast carcinoma (1 paper); Cirrhosis (1); colorectal cancer (1); fibrosis (1); kidney disease (1); liver fibrosis (1); prostate carcinoma (1).